GRN (granulin precursor)
Diseases named in the same sentence as GRN in open-access papers (continued):
Sharing a sentence is not in itself a finding about the gene and the disease.
ischemic stroke (5 papers, 2007 to 2022). A stroke disorder caused by obstruction of blood flow to the brain, due to thrombotic (local blood clot formation) or embolic (due to a blood clot or other material traveling from another site) event. "Many of the identified genes, including TLR2, TLR3, TLR9, GRN, COL1A1, FN1, and LAMB1, were reported as upregulated genes in previous reports of ischemic stroke." (PMID 35887140, 2022).
Lewy body dementia (5 papers, 2013 to 2025). A progressive form of dementia characterized by the presence of protein deposits called Lewy bodies in the midbrain and cerebral cortex, and loss of cholinergic and dopaminergic neurons. "This pleomorphism is expanded by the recent association of GRN rare variants in autopsy confirmed cases with Lewy Body dementia (LBD)." (PMID 29091718, 2017). "Mutations in GRN, the gene that encodes PGRN, cause familial frontotemporal lobar dementia (FTLD) and Lewy body dementia (LBD)." (PMID 36233357, 2022). "There is a known link with AD and Lewy body disease, but to date there are no data regarding SVD in patients carrying a GRN mutation." (PMID 29370838, 2018).
myeloma (5 papers, 2007 to 2025). "Cancers of the skin, breast, astrocytoma, lung, ovary, uterus, head and neck, liver, lymphoma, multiple myeloma, and leukemia all have GRN as a tumor promoter." (PMID 37091137, 2023). "In our cellular interaction analysis, myeloma cells displayed an upregulation of inflammatory cytokines (e.g., CCL3, GRN, AREG, and MIF) that target receptors primarily expressed in the myeloid and dendritic cell compartment." (PMID 34845188, 2021).
Stroke (5 papers, 2015 to 2025). Sudden impairment of blood flow to a part of the brain due to occlusion or rupture of an artery to the brain. "Additionally, given that microglia-derived lipid components are essential for remyelination, IPAM might be pivotal for post-stroke remyelination by releasing lipid metabolites and oligodendrotrophic factors, such as GRN." (PMID 38082331, 2023).
chronic lymphocytic leukemia (4 papers, 2013 to 2021). "Using microarray based gene expression profiling we have recently demonstrated that the gene for Pgrn, granulin (GRN), is significantly higher expressed in aggressive CD38+ZAP-70+ as compared to indolent CD38−ZAP-70− chronic lymphocytic leukemia (CLL) cases." (PMID 24009671, 2013).
language disorder (4 papers, 2016 to 2024). A category of disorders characterized by an impairment in the development of an individual's language capabilities, which is in contrast to his/her non-verbal intellect. "The findings have implications for understanding the language disorder associated with GRN mutations." (PMID 39387948, 2024). "GRN-FTD usually affects the frontal and temporal cortices, leading to behavioral changes, executive dysfunction, and language disorders." (PMID 38291418, 2024). "The fourth language disorder, lvPPA, did not share any of its four genes (APOE, APP, GRN, MAPT) with the other disorders." (PMID 34539327, 2021).
liver fibrosis (4 papers, 2018 to 2024). "Interestingly, GRN has been recently reported as a key player also in pancreatic cancer metastasis, where macrophage-derived GRN induces liver fibrosis and contributes to cytotoxic CD8+ T-cell exclusion in metastatic livers." (PMID 32626702, 2020). "However, emodin administration was able to decrease the hepatic expression of IL-1β, TNF-α, GRN, and TGF-β1 in the liver fibrosis model, which also explains why emodin can alleviate liver inflammation and fibrosis." (PMID 29743924, 2018).
pancreatic cancer (4 papers, 2019 to 2022). "Of interest, GRN was shown to induce the differentiation of CAFs from resident fibroblasts in breast and pancreatic cancer." (PMID 31200555, 2019). "In vitro experiments further revealed that macrophages upregulated GRN expression when they were cultured in pancreatic cancer cell line-conditioned medium or stimulated to acquire an M2-like phenotype." (PMID 31200555, 2019). "GRN was previously shown to mediate the acquisition of cancer-associated fibroblast (CAF)-like phenotypes in resident fibroblasts in the context of breast and pancreatic carcinomas." (PMID 31200555, 2019).
Cerebral ischemia (3 papers, 2022 to 2024). Restriction of arterial blood supply to the brain associated with insufficient oxygenation to support the metabolic requirements of the tissue. "GRN was involved in a pro-inflammatory response at the early stages after cerebral ischemia." (PMID 38166912, 2024).
motor neuron degeneration (3 papers, 2010 to 2023). "In ALS, causal genetic variants in GRN, segregating with the disease, have not been observed so far, but GRN seems to act as a genetic modifier of the degree of motor neuron degeneration." (PMID 36831264, 2023). "Another common mutation of familial FTLD-TDP is progranulin (GRN), which is clinically associated with the pure FTD form with an absence of motor neuron degeneration." (PMID 36555399, 2022).
acne (2 papers, 2024). An inflammatory process of the sebaceous glands which is characterized by comedones, nodules, papules and/or pustules on the skin. "Given that TREM2 macrophages have been implicated in driving inflammation in acne, our subsequent analyses focused on the function of GRN within these cells." (PMID 39143467, 2024). "Together, our findings shed light on the complex interplay between inflammation and hyperkeratinization in acne pathogenesis, while also highlighting GRN and IL-13RA1 as promising therapeutic targets for acne." (PMID 38854033, 2024). "Activation of GRN and IL-13RA1 exacerbates inflammation and hyperkeratinization both of which are critical in acne progression." (PMID 38854033, 2024). "Further exploration of their functional roles in vitro revealed that GRN may exacerbate acne progression by enhancing inflammation in TREM2 macrophages, as demonstrated by its induction of inflammatory cytokines and chemokine expression." (PMID 38854033, 2024). "Next, to spatially localize GRN and IL-13RA1 expression in acne skin, we used our previously published Seq-Scope sequencing dataset obtained from acne lesions and segmented the histological area using 10 μm-sided square grids, each grid detected an average of 145 genes across 3558 grids." (PMID 39143467, 2024). "Our findings suggest that GRN and IL-13RA1 are key players in the inflammation and hyperkeratinization process during acne development, highlighting their potential as novel therapeutic targets for acne treatment." (PMID 38854033, 2024). "Furthermore, SORT1 was found to colocalize with GRN in acne lesions." (PMID 38854033, 2024). "Subsequently, we focused on the function of GRN and IL-13RA1 in TREM2 macrophages and keratinocytes as these cells participate in inflammation and hyperkeratinization in the early stages of acne development." (PMID 38854033, 2024). "Our subsequent focus centered on examining the roles of GRN in TREM2 macrophages and IL-13RA1 in keratinocyte basal cells given their consistent alterations across donors and potential importance in acne development." (PMID 38854033, 2024). "Our data collectively suggest that inflammation and hyperkeratinization, driven by common dysregulated GRN and IL13RA1 may be pivotal in acne development." (PMID 38854033, 2024).
apraxia (2 papers, 2024 to 2025). Apraxia is a neurological disorder characterized by the inability to perform tasks or movements, despite having the desire and physical ability to perform them. "Speech apraxia (articulatory problems) is uncommon in nfvPPA cases caused by GRN mutations and TDP-43 pathology, as it is usually associated with tau pathology." (PMID 40234992, 2025). "On the other hand, patient 17, as well as other patients with TDP-A and GRN mutations, were recorded as showing relative preservation of praxic skills in relation to activities of daily living, contrasting with their severe apraxia on formal testing." (PMID 39387948, 2024).
Cerebral atrophy (2 papers, 2023 to 2025). Atrophy (wasting, decrease in size of cells or tissue) affecting the cerebrum. "Additionally, it is worth noting that GRN mutations are associated with a widespread pattern of cerebral atrophy, whereas MAPT mutations primarily result in atrophy in specific regions, such as the anteromedial temporal region." (PMID 37762113, 2023). "Two studies reported associations between circulating TNFα and increased cerebral atrophy, particularly in MAPT-FTD patients, but not in those with C9ORF72- or GRN-mediated FTD." (PMID 40305176, 2025).
colon cancer (2 papers, 2023 to 2024). "ZNF91 is another key regulator according to UC GRN, along with 44 other TFs, and regulates 397 UC common overregulated DEGs, co-expressed in colon cancer and related to transmembrane transport, mitochondrial function, and multiple metabolic pathways and diseases." (PMID 39791702, 2024).
esophageal cancer (2 papers, 2013 to 2023). A primary or metastatic malignant neoplasm involving the esophagus. "GRN is an autocrine growth factor closely related with the onset and development of various tumors, such as ovarian and esophageal cancer." (PMID 24349832, 2013).
gangliosidosis (2 papers, 2022 to 2023). A group of autosomal recessive lysosomal storage disorders marked by the accumulation of gangliosides. "Here we discover that PGRN deficiency in cells, murine brains, or human frontal lobes of subjects with FTD due to GRN mutations, results in gangliosidosis." (PMID 36207292, 2022). "The authors hypothesized that PGRN and/or GRN peptides facilitate GG catabolism by maintaining BMP levels and that PGRN and/or GRN deficiency in lysosomes leads to gangliosidosis." (PMID 38203300, 2023).
genitourinary cancers (2 papers, 2020 to 2021). "Of the target genes regulated by miR-107, GRN is notable due to its overexpression in several cancer cell lines, including lung, breast, hepatic, gastrointestinal, and genitourinary cancers." (PMID 32883962, 2020).
leukemia (2 papers, 2019 to 2023). A malignant (clonal) hematologic disorder, involving hematopoietic stem cells and characterized by the presence of primitive or atypical myeloid or lymphoid cells in the bone marrow and the blood. "As we detected strong GRN expression in myeloid cells, we performed adoptive transfer of Eμ-TCL1 leukemia cells to bone marrow chimeric Grn−/− mice that lack GRN in hematopoietic cells." (PMID 31200555, 2019).
Listeria monocytogenes infection (2 papers, 2013 to 2016). "GRN-deficient mice failed to clear Listeria monocytogenes infection and allowed bacteria to proliferate, and also showed a substantial reduction in serum amounts of TNF-α and IL-6 upon administration of CpG-ODNs." (PMID 23755248, 2013).
mesothelioma (2 papers, 2018 to 2022). A usually malignant and aggressive neoplasm of the mesothelium which is often associated with exposure to asbestos. "To further decipher the contribution of EphA2 in modulating the progranulin axis in mesothelioma, we generated MSTO-211H and NCI-H2052 cells with genetic deletion of EphA2 by CRISPR/Cas9 technology and compared the ability of GRN- and EphA2-KO cells to migrate and invade through matrigel." (PMID 36471440, 2022). "Among the ID4-dependent angiogenesis-related genes upregulated in macrophages, GRN particularly attracted our attention, because this growth factor is specifically expressed in TNBC and BLBC and has recently been correlated to tumour angiogenesis in mesothelioma." (PMID 29921315, 2018). "However, the phenotypes of GRN- and EphA2-deleted cells considerably differed in their migratory, invasive and in vivo tumor formation ability, thereby suggesting that EphA2 might not be the major functional progranulin receptor in mesothelioma." (PMID 36471440, 2022).
Onset (2 papers, 2018 to 2023). The age group in which disease manifestations appear. "Both the PSEN1 and PSEN2 variants were found in late-onset PD individuals whereas the GRN variant was found in one control." (PMID 29692703, 2018). "Both APP p.R499C and p.R397T were found in late-onset PD (LOPD; AAO >50 years) patients whereas APP (p.Q138R) and GRN (p.C260R) were found in controls." (PMID 29692703, 2018).
posterior cortical atrophy (2 papers, 2016). Posterior Cortical Atrophy (PCA) is a rare progressive neurodegenerative disorder with a typical onset between 50-65 years of age characterized by progressive impairment of higher visual processing skills and other posterior cortical functions without any evidence of ocular abnormalities. "No unclear or pathogenic GRN variants were found in patients diagnosed with AD in our cohort, except the p.P209L variant that was found in a patient with posterior cortical atrophy." (PMID 27632209, 2016).
retinal degeneration (2 papers, 2021). Degeneration of the retina. "Retinal degeneration leading to visual dysfunction and blindness has been reported as a typical symptom in patients with FTD and NCL with GRN gene mutations." (PMID 34768987, 2021).
squamous cell carcinoma (2 papers, 2021). A carcinoma arising from squamous epithelial cells. "Compared with adenocarcinoma, squamous cell carcinoma showed strong communications with endothelial by the MIF/TNFRSF10D, EGFR/GRN, EGFR/HBEGF, and EPHB2/EFNB2 interactions." (PMID 34185421, 2021).
autoimmune thyroid disease (1 paper, 2023). Inflammatory disease of the thyroid gland due to autoimmune responses leading to lymphocytic infiltration of the gland. "Meanwhile, antigen processing and presentation, autoimmune thyroid disease, cytokine and cytokine receptor interaction, chemokine signaling pathway, which are associated with tumor immunity, were also enriched in GRN co-expressed genes." (PMID 37660003, 2023).
cerebral small vessel disease (1 paper, 2018). Cerebral small vessel disease is the term currently used to pathological processes that affect the brain parenchymal circulation (arterioles, capillaries, and veins). "Because the penetrance rate of the clinical phenotype of carriers of GRN mutations is age-dependent, further research is required to investigate the role of co-occurring age-related pathologies such as AD, PART, and cerebral small vessel disease." (PMID 29370838, 2018).
cocaine use disorder (1 paper, 2024). A substance-related disorder that involves the recurring use of cocaine despite negative consequences. "We explored whether broad gene expression changes of GRN-identified targets could be observed in the 3-crit model of cocaine use disorder." (PMID 39184101, 2024).
Dystonia (1 paper, 2025). An abnormally increased muscular tone that causes fixed abnormal postures. "Meanwhile, cases classified as “quite inconsistent” were mostly focal (n = 15) or segmental/multifocal (n = 8) dystonia and involved variants in genes typically associated with other disorders where dystonia is rarely reported, such as C19orf12, GRN, KIF1A, and PRKCG." (PMID 40533913, 2025). "This suggests that dystonia may occur without or prior to cognitive and behavioral symptoms due to GRN variants." (PMID 40533913, 2025).
HIV-1 infection (1 paper, 2024). The type species of lentivirus and the etiologic agent of acquired immunodeficiency syndrome (AIDS). "In line with this, partial knock-out (KO) of GRN in CEM-M7-Cas9 cells significantly increased HIV-1 infection." (PMID 38714682, 2024).
Leukoencephalopathy (1 paper, 2024). This term describes abnormality of the white matter of the cerebrum resulting from damage to the myelin sheaths of nerve cells. "In our analyses, TREM2, TYROBP, and GRN associated with leukoencephalopathy and FTD, show correlated gene expression, however, SMCR8 and WDR41, known to form a complex with C9orf72, did not." (PMID 38469573, 2024).
Nasu-Hakola disease (1 paper, 2020). "In patients diagnosed with AD we found three C9orf72 expansions, nine DVs in MAPT, five in CSF1R, two in GRN, three in PRNP and one each in SQSTM1, TARDBP and VCP, as well as a homozygous TREM2 DV normally associated with Nasu-Hakola disease." (PMID 30279455, 2020).
osteosarcoma (1 paper, 2025). A usually aggressive malignant bone-forming mesenchymal neoplasm, predominantly affecting adolescents and young adults. "Collectively, GRN supports the proliferation, migration, and invasion of osteosarcoma cells in vitro." (PMID 41488055, 2025). "Based on its model weight, prognostic relevance, and tumor/stroma-centered localization, we prioritized GRN as a key gene for subsequent analyses to elucidate its role in osteosarcoma." (PMID 41488055, 2025). "GRN silencing reduced proliferation, clonogenicity, migration, and invasion in osteosarcoma cells." (PMID 41488055, 2025). "Collectively, elevated GRN marks a TME that is quantitatively and qualitatively immunosuppressed in osteosarcoma." (PMID 41488055, 2025).
pancreatic ductal adenocarcinoma (1 paper, 2022). An infiltrating adenocarcinoma that arises from the epithelial cells of the pancreas. "Granulin (GRN) is highly expressed in multiple tumors and can restore the infiltration of CD8+ T cells in pancreatic ductal adenocarcinoma, indicating that immunotherapy targeting macrophage-derived GRN is promising." (PMID 36248886, 2022).
Paranoia (1 paper, 2022). The feeling and belief that one is being targeted or is a focus of negative or untoward actions, overt or covert, from others. "Progranulin (GRN) mutations are associated with a constellation of psychiatric manifestations in frontotemporal dementia, including sexual disinhibition, over-ritualistic behavior, paranoia, and visual hallucinations." (PMID 36160603, 2022).
perinatal asphyxia (1 paper, 2016). A disorder caused by a lack of blood flow or gas exchange to or from the fetus in the period immediately before, during, or after the birth process. "In order to evaluate whether the hypoxia-induced miR-659-mediated regulation of PGRN takes place also in vivo, GRN mRNA, and miR-659-3p levels were measured in a rat model of global perinatal asphyxia." (PMID 27199656, 2016).
primary progressive multiple sclerosis (1 paper, 2021). A multiple sclerosis that is characterized by steady worsening of neurologic functioning, without any distinct relapses or periods of remission. "In addition to AD, GRN haplotypes may influence the risk of other neurodegenerative disease like primary progressive multiple sclerosis in a gender-specific manner." (PMID 34103390, 2021).
retinoblastoma (1 paper, 2025). A malignant tumor that originates in the nuclear layer of the retina. "For example, in retinoblastoma, TAMs express GRN, which can increase their angiogenic potential and promote tumor progression." (PMID 41211507, 2025).
Senile plaques (1 paper, 2019). Senile plaques are extracellular deposits of amyloid in the gray matter of the brain. "Initial papers observed features of PGRN immunoreactivity in microglia around senile plaques in AD cases when comparison was being made with neuropathological features of FTLD due to GRN mutations." (PMID 30862089, 2019).
teratoma (1 paper, 2007). A non-seminomatous germ cell tumor characterized by the presence of various tissues which correspond to the different germinal layers (endoderm, mesoderm, and ectoderm). "PC cell-derived growth factor (PCDGF), also called epithelin/granulin precursor (GEP), is an 88-kDa secreted glycoprotein purified from the conditioned medium of the highly malignant mouse teratoma-derived cell line PC for its ability to stimulate proliferation in an autocrine fashion." (PMID 17261172, 2007).